PCDHB8 (protocadherin beta 8)
Description:
Calcium-dependent cell-adhesion protein involved in cells self-recognition and non-self discrimination. Thereby, it is involved in the establishment and maintenance of specific neuronal connections in the brain.
Synonyms: PCDH3I; PCDH-BETA8
Tractability: Antibody: UniProt places it where antibodies can reach, with medium confidence; UniProt predicts a signal peptide or a membrane-spanning region; its Gene Ontology location is reachable by antibodies, with medium confidence.
Gene: Protein-coding gene on chromosome 5 (141,177,790 to 141,182,369, forward strand). Ensembl gene ENSG00000120322.
Subcellular location: Cell membrane
Gene Ontology:
Molecular function: calcium ion binding; cell adhesion molecule binding; identical protein binding
Biological process: cell adhesion; homophilic cell-cell adhesion; nervous system development
Cellular component: plasma membrane; membrane
Genetic constraint (gnomAD): Loss-of-function variants: 1 observed, 0.6 expected, observed/expected ratio (o/e) 1.66, 90% interval 0.32 to 1.92. That is too few expected variants to judge how well the gene tolerates losing a copy. Missense variants: 821 observed, 772.13 expected, observed/expected ratio (o/e) 1.06, 90% interval 1 to 1.13. Synonymous variants: 383 observed, 336.37 expected, observed/expected ratio (o/e) 1.14, 90% interval 1.05 to 1.24.
Homologues: Orthologues: macaque PCDHB8 (92% identical). Paralogues in human: PCDHB13 (92% identical), PCDHB16 (77% identical), PCDHB3 (75% identical), PCDHB11 (74% identical), PCDHB15 (74% identical), PCDHB2 (74% identical), PCDHB5 (74% identical), PCDHB14 (73% identical), PCDHB4 (73% identical), PCDHB10 (73% identical), PCDHB12 (73% identical), PCDHB6 (73% identical), and 49 more.
Diseases named in the same sentence as PCDHB8 in open-access papers:
PCDHB8 is named in the same sentence as 2 diseases in open-access papers, as found by Europe PMC text mining. Sharing a sentence is not in itself a finding about the gene and the disease. The quoted sentences say what the papers report.
tumour (2 papers, 2009 to 2020). "PCDHB8 and PCDHB15 exhibited strong methylation associated silencing but PCDHB12 was not consistently down-regulated in tumours, despite hypermethylation." (PMID 19956686, 2009).
PCDHB8 also shares sentences with these, for which no sentence is quoted: cancer (1 paper).